CHAF1A (chromatin assembly factor 1 subunit A)
Diseases named in the same sentence as CHAF1A in open-access papers (continued):
Sharing a sentence is not in itself a finding about the gene and the disease.
cancer (continued). "In this study, we have reported CHAF1A was overexpressed in 20 types of cancers." (PMID 36968583, 2023). "Using TIMER 2.0 database, the gene expression of CHAF1A was investigated in various cancer types." (PMID 36968583, 2023). "More importantly, it was found that CHAF1A could affect cancer metabolism and immune system." (PMID 36968583, 2023). "Elevated expression of CHAF1A has been reported to be associated with several solid cancers, it was found that this phenomenon was commonly shared in more cancer types, indicating that abnormal higher expression of CHAF1A could be a potential biomarker for cancer diagnosis." (PMID 36968583, 2023). "Taken together, these observations suggest that CHAF1A inactivation can enable BRCA-deficient cells to avert replication-coupled DNA damage, thereby driving chemoresistance and potentially exacerbating adverse clinical outcomes in patients with BRCA1/2 mutated cancers." (PMID 36085347, 2022). "High expression of CHAF1A enables cancer cells to enhance the TLS pathway in response to endogenous and exogenous DNA damage, improve the survival ability of cancer cells, and then promote cancer progression." (PMID 40025006, 2025). "In summary, our study identified CHAF1A as a key regulator of TLS pathway in cancer cells and CHAF1A promotes cancer cell survive by regulating the TLS pathway." (PMID 40025006, 2025). "CHAF1A facilitates PCNA K164 monoubiquitination mediated by RAD18, thereby promoting the recruitment of Y-family DNA polymerases and enhancing cancer cell resistance to DNA damage." (PMID 40025006, 2025). "Knockdown of CHAF1A or PCNA significantly inhibits EC cell proliferation and DNA replication rates, which is consistent with studies in other cancers." (PMID 37189802, 2023). "It has been widely reported that CHAF1A and PCNA co-regulate histone assembly to promote cancer progression." (PMID 37189802, 2023). "However, there is paucity information about the clinical significance, functions and co-expressed gene network of CHAF1A, the major subunit in CAF-1, in cancer." (PMID 36968583, 2023). "Because of the high correlation between CHAF1A and PCNA expression, we hypothesized that CHAF1A and PCNA promote the progression of EC through the synergistic acceleration of cancer cell DNA replication." (PMID 37189802, 2023). "Although the expression and interactions of CHAF1A and PCNA have been studied in other cancers, their roles in EC remain unclear." (PMID 37189802, 2023). "Functional experiments suggest that CHAF1A may act as a co-activator of the Wnt pathway, interacting with TCF4 and increasing the expression of c-MYC and CCND1 to promote cancer cell proliferation." (PMID 34073937, 2021).
infection (2 papers, 2022 to 2024). The state of being infected such as from the introduction of a foreign agent such as serum, vaccine, antigenic substance or organism. "Together, these results indicated that CHAF1A participates in pathogen infection and mediates the oncogenic roles of some pathogens." (PMID 38254099, 2024). "In our study, we revealed that EBV infection induced CHAF1A expression, and GSEA suggested that CHAF1A was associated with many infection signaling pathways involving both bacteria and viruses." (PMID 38254099, 2024). "Recently, CHAF1A is reported to play a role in the infection of human immunodeficiency virus 1 (HIV-1) and be critical in the establishment and maintenance of HIV-1 latency." (PMID 38254099, 2024). "We further utilized the lentivirus infection method to attenuate CHAF1A expressions in SPOP-deleted cells and found that CHAF1A knockdown significantly impaired the malignant features of SPOP-deficient DLBCL." (PMID 35773729, 2022). "The qRT-PCR experiments further showed the overexpression of CHAF1A in DLBCL cells via infection." (PMID 35773729, 2022).
CHAF1A also shares sentences with these, for which no sentence is quoted: lung carcinoma (2 papers); bladder urothelial carcinoma (1); choriocarcinoma (1); colorectal cancer (1); Ewing sarcoma (1); Gestational Diabetes Mellitus (1); leukaemias (1); liver (1); lymph node metastasis (1); malaria (1); oral cancers (1); prostate squamous cell carcinoma (1); renal cell carcinoma (1); triple-negative breast carcinoma (1).